TTN-AS1 (TTN antisense RNA 1)
Synonyms: LOC101927055
Gene: Long non-coding RNA gene on chromosome 2 (178,521,183 to 178,779,963, forward strand). Ensembl gene ENSG00000237298.
Diseases named in the same sentence as TTN-AS1 in open-access papers:
TTN-AS1 is named in the same sentence as 17 diseases in open-access papers, as found by Europe PMC text mining. Sharing a sentence is not in itself a finding about the gene and the disease. The quoted sentences say what the papers report.
breast carcinoma (2 papers, 2020 to 2021). "Owing to the complex regulatory mechanism of TTN-AS1 in breast cancer by regulating the miR-524-5p/RRM2 axis or miR-139-5p/ZEBI axis, the effect of TTN-AS1 on OSCC progression might involve other miRNAs or mRNAs, which needs to be explored further." (PMID 34606420, 2021). "In addition, TTN-AS1 has been shown to promote breast cancer progression by different miRNA/mRNA axes, including miR-524-5p/RRM2 and miR-139-5p/ZEBI, which suggests that the regulatory mechanism of TTN-AS1 in OSCC progression might be involved in multiple molecules." (PMID 34606420, 2021).
esophageal squamous cell carcinoma (2 papers, 2019 to 2022). Esophageal squamous cell carcinoma (ESCC) is a type of esophageal carcinoma (EC) that can affect any part of the esophagus, but is usually located in the upper or middle third. "Moreover, the overexpression of TTN-AS1 is implicated in many tumor types including hepatocellular carcinoma, esophageal squamous cell carcinoma, and lung adenocarcinoma." (PMID 31525734, 2019). "LncRNA Titin-antisense RNA1 (TTN-AS1) has been reported to be involved in tumorigenesis in various type cancers, including esophageal squamous cell carcinoma (ESCC), cervical cancer, gastric cancer and lung cancer." (PMID 35928868, 2022). "In recent years, an lncRNA called TTN antisense RNA 1 (TTN-AS1) was reported to be overexpressed and play oncogenic roles in cervical cancer, papillary thyroid cancer, gastric cancer, hepatocellular carcinoma, esophageal squamous cell carcinoma, and lung adenocarcinoma." (PMID 31525734, 2019).
gastric cancer (2 papers, 2019 to 2023). A primary or metastatic malignant neoplasm involving the stomach. "Additionally, TTN-AS1 is overexpressed in gastric cancer tissues and cell lines; this overexpression negatively correlates with overall survival of these patients." (PMID 31525734, 2019). "In gastric cancer, high TTN‐AS1 expression contributed to the poor OS and tumor progression by the TTN‐AS1‐miR‐376b‐3p‐KLF12 axis." (PMID 37528740, 2023).
hepatocellular carcinoma (2 papers, 2019 to 2021). A malignant tumor that arises from hepatocytes. "Reportedly, long non-coding RNAs (lncRNAs) are implicated in hepatocellular carcinoma (HCC) progression, yet little is known concerning the biological functions of TTN antisense RNA 1 (TTN-AS1) in HCC." (PMID 33517826, 2021).
melanoma (2 papers, 2021 to 2022). A malignant, usually aggressive tumor composed of atypical, neoplastic melanocytes. "Moreover, TTN-AS1 is also highly expressed in melanoma tissues." (PMID 35096622, 2021). "For instance, SNHG16, TTN-AS1, and MALAT1 are overexpressed in melanoma and exert oncogenic effects." (PMID 33674778, 2022).
ovarian carcinoma (2 papers, 2022 to 2025). A malignant neoplasm originating from the surface ovarian epithelium. "In addition, knockdown of FBXW7 can weaken the effect of TTN-AS1 upregulation on cell behavior, suggesting that TTN-AS1 exerts its biological behavior by upregulating FBXW7 in ovarian cancer cells." (PMID 40534867, 2025). "Moreover, knockdown of FBXW7 attenuated the functions of TTN-AS1 upregulation on cell behaviors, suggesting that TTN-AS1 exerts its biological behaviors via upregulating FBXW7 in ovarian cancer cells." (PMID 35928868, 2022).
cholangiocarcinoma (1 paper, 2024). A carcinoma that arises from the intrahepatic biliary tree (intrahepatic cholangiocarcinoma) or from the junction, or adjacent to the junction, of the right and left hepatic ducts (hilar cholangiocarcinoma). "Addressing this question would provide a comprehensive understanding of the role of TTN-AS1 in exosomes secreted by cholangiocarcinoma tumor cells and hold significant guiding implications for utilizing exosomal LncRNA TTN-AS1 as a novel target for cholangiocarcinoma diagnosis and treatment." (PMID 38637832, 2024). "Genes such as TTN-AS1, which exhibited notably elevated expression in extracellular vesicles secreted by cholangiocarcinoma tumor cells, hold promise as potential biomarkers for cholangiocarcinoma diagnosis and treatment." (PMID 38637832, 2024).
clear cell renal cell carcinoma (1 paper, 2021). "For example, TTN-AS1 regulates the TTN-AS1/miR-195/cyclin D1 axis through sponge adsorption so as to promote tumor cell proliferation and modulate tumor cell cycle activities in clear cell renal cell carcinoma." (PMID 34671381, 2021).
glioblastoma (1 paper, 2021). The most malignant astrocytic tumor (WHO grade IV). "Based on these studies, circMM9 is a ceRNA that targets miR-124, while LINC00680 and TTNAS1 are ceRNAs that target miR-320b in glioblastoma cells." (PMID 34458150, 2021). "EIF4A3 is overexpressed in glioblastoma and is related to two lncRNAs, LINC00680 and TTNAS1, that promote the malignant behavior of glioblastoma cells." (PMID 34458150, 2021). "That study showed that when the expression of EIF4A3, LINC00680, and TTNAS1 was downregulated in PANC-1 and SW1990 cells, their proliferation, migration, and invasion was impaired, while tumor growth was inhibited in vivo and glioblastoma cell apoptosis was promoted." (PMID 34458150, 2021).
cancer (10 papers, 2019 to 2023). A tumor composed of atypical neoplastic, often pleomorphic cells that invade other tissues. "Increasing evidence has demonstrated that high TTN‐AS1 expression is highly related to poor prognosis in diverse human cancers." (PMID 37528740, 2023). "Titin antisense RNA 1 (TTN-AS1) is a novel lncRNA that takes part in the regulation of cancer development in accordance with existing researches." (PMID 32863773, 2020). "TTN-AS1, a recently identified oncogene, has been proved to participate the progression of numerous cancers." (PMID 31363080, 2019). "Taken together, our findings suggested that increased TTN‐AS1 expression implied a worse prognosis, indicating that TTN‐AS1 expression might be served as a promising biomarker for prognosis in various cancers." (PMID 37528740, 2023). "TTN-AS1 is a lncRNA that binds to titin mRNA and has pro-oncogenic effects in many cancers." (PMID 36119544, 2022). "However, TTN-AS1 has also recently been proposed as an oncogene across various cancers and one suggested mode of action has been dysregulation caused by the creation of competing endogenous RNA." (PMID 33094325, 2021). "The dysregulation of lncRNA TTN antisense RNA 1 (TTN-AS1) has been found in malignancies." (PMID 34090483, 2021). "LncRNA titin antisense RNA 1 (TTN-AS1) is known as a crucial regulatory factor in several cancers." (PMID 32863773, 2020). "In HCC, TTN-AS1 knockdown could induce the apoptosis of cancer cells." (PMID 33517826, 2021).
tumor (8 papers, 2019 to 2024). "Meanwhile, increased TTN‐AS1 expression is closely related to advanced tumor differentiation and tumor malignancy as well." (PMID 37528740, 2023). "The qRT-PCR analyses revealed that CCA tumor tissues expressed significantly higher levels of TTN-AS1 and NRP-1 mRNA, and significantly lower levels of miR-320a, compared with adjacent normal bile duct tissues." (PMID 32801339, 2020). "Furthermore, we also found that high TTN‐AS1 expression rendered more advanced clinical stage, lymph node metastases, larger tumor size, and worse tumor differentiation when compared with low TTN‐AS1 expression." (PMID 37528740, 2023). "Similarly, in our study, TTN-AS1 silencing retarded the OS tumor growth, thereby corroborating the anticarcinogenic effect of TTN-AS1 silencing on OS tumor progression in vivo." (PMID 34141611, 2021). "Next, our study indicates that TTN-AS1 expression is associated with tumor differentiation, T-stage, and lymph node metastasis, but we did not explore the correlation between TTN-AS1 expression and prognosis of OSCC due to the recently collected tissues." (PMID 34606420, 2021). "Additionally, TTN‐AS1 was also revealed to accelerate epithelial‐mesenchymal transition (EMT), tumor angiogenesis, and cell cycle progression by downregulating miR‐320a, thus promoting the migration and proliferation of cholangiocarcinoma." (PMID 37528740, 2023).
TTN-AS1 also shares sentences with these, for which no sentence is quoted: colorectal cancer (2 papers); lung adenocarcinoma (2); cervical cancer (1); glioma (1); osteosarcoma (1); papillary thyroid cancer (1).